PPARG (peroxisome proliferator activated receptor gamma)
Diseases named in the same sentence as PPARG in open-access papers (continued):
Sharing a sentence is not in itself a finding about the gene and the disease.
cancer (continued). "The NRs associated with cancers include the retinoic acid receptors (RARs), the retinoid X receptors (RXRs), the peroxisome-proliferator-activated receptor γ (PPARγ), and the vitamin D receptor (VDR)." (PMID 35631448, 2022). "Recently, two meta-analyses reported that the PPARγ rs3856806 C > T variant increased overall cancer susceptibility." (PMID 36587194, 2022). "Insufficient PPARγ ligands can significantly downregulate the activity of PPARγ, thus causing the PPARγ system unable to attack cancer cells." (PMID 34557159, 2021). "PPARγ plays a crucial role in the metabolic reprogramming of cancer-associated fibroblasts and adipocytes, coercing the two stromal cells to become substrate donors for cancer growth." (PMID 33946986, 2021). "PPARγ–DNMT1 co-expression is associated with several cancers while the evolutionary action (EA) score revealed PPARγ variants to be more of an oncogenic type." (PMID 34439147, 2021). "Given the tight association with the well‐known tumor suppressor protein PTEN, PPARγ and its associated signaling found value in the pathogenesis of different human cancers." (PMID 34549887, 2021). "Kaplan-Meier analysis revealed that the positive expression of nuclear PPARγ in cancer tissues was associated with short overall survival time in PDAC patients (p = 0.0290)." (PMID 35186942, 2021). "The cancer-related loss-of-function PPARγ mutations have been found predominantly throughout the LBD of the PPARG gene with varying degree of impaired ability in inducing transactivation of target genes." (PMID 34680260, 2021). "To uncover underlying molecular mechanisms between helix H3 mutations and tumorigenesis, we performed structure‒function studies on the PPARγ LBDs containing helix H3 mutations found in cancers." (PMID 33266062, 2020). "Owing to the ongoing discovery of PPARG mutations in various cancers, the molecular basis of PPARγ mutations found in cancers would be an emerging topic of great importance." (PMID 33266062, 2020). "We identified PPARG mutations from publicly available genomic databases or cancer-related publications and evaluated the structure–function relationship." (PMID 33266062, 2020). "For example, high PPARG expression correlated with decreased mortality risk for five cancer types (BLCA, BRCA, KIRC, READ, and STAD) and increased risk for eight cancer types (CESC, HNSC, LIHC, LUAD, PAAD, PCPG, SARC, THCA)." (PMID 32024906, 2020). "Helix H3 of the PPARγ ligand-binding domain (LBD) is essential for ligand binding and PPARγ activation and harbors a relatively large number of sites that are mutated in cancers." (PMID 33266062, 2020). "In contrast, other helix H3 mutations found in various cancers impair ligand binding essential for transcriptional activity of PPARγ." (PMID 33266062, 2020). "Two aims were proposed by the original researchers: (a) to investigate the connection between the PPARγ rs1801282 variant and the risk of cancer and (b) to determine the influence of NSAID usage on thwarting cancer." (PMID 32513119, 2020). "In this study, we performed bioinformatics, structural and biochemical analyses to characterize PPARγ LBDs with helix H3 mutations found in cancers." (PMID 33266062, 2020). "Recently, a meta-analysis reported that the PPARG rs3856806 C>T polymorphism increased the risk of overall cancer." (PMID 30838172, 2019). "Several studies have shown decreased PPARγ expression in association with chronic inflammation in cancers." (PMID 31311204, 2019). "The overexpression of PPARG was closely associated with the increased copy-number from genome identification of significant targets in cancer (GISTIC) analysis." (PMID 30845932, 2019). "By contrast, the PPARγ gain-of-function mutations identified here are also observed in other types of cancer." (PMID 30651555, 2019). "A meta-analysis indicated the PPARG c.34C>G polymorphism was associated with the risk of cancer in Asians." (PMID 29254243, 2017).
cancer (continued). "Several individual studies have reported positive signals of PPARG c.1347C>T polymorphism with cancer risk; however, others observed null association." (PMID 29254243, 2017). "In conclusion, the nine nsSNP PPARγ variants associated with metabolic disorders and /or cancer show alterations in the dynamics and tertiary contacts that impair the correct reciprocal positioning of H3 and H12, crucially important for PPARγ functioning." (PMID 28208577, 2017). "Recently, several studies suggested that PPARG c.1347C>T polymorphism was correlated with cancer risk." (PMID 29254243, 2017). "Although more and more case-control studies focused on the relationship of the PPARG c.1347C>T polymorphism with cancer susceptibility, the obtained findings remained conflicting." (PMID 29254243, 2017). "To address the association between PPARG c.1347C>T polymorphism and cancer risk more precisely, we carried out a comprehensive meta-analysis." (PMID 29254243, 2017). "The ability of TZDs to inhibit a number of cancers has been associated with their ability to suppress growth and stimulate apoptosis in a PPARγ-dependent manner." (PMID 28460464, 2017). "Along with a meta-analysis, we found that PPARG c.1347C>T polymorphism was associated with the increased risk of overall cancer." (PMID 29254243, 2017). "Agonistic PPARγ augments glucose uptake and oxidation of fatty acids, two metabolic events recently associated with cancer cell-immune cell energy competition." (PMID 28740126, 2017). "In a subgroup analysis by ethnicity, evidence of significant association between PPARG c.1347C>T polymorphism and cancer risk was found among Asians and mixed populations." (PMID 29254243, 2017). "Nevertheless, for some practical reasons, we hope that more case-control studies with the detailed environmental data to further explore the molecular mechanism of PPARG c.1347C>T polymorphism with development of cancer." (PMID 29254243, 2017). "Next, we carried out a pooled analysis to determine the potential relationship between PPARG c.1347C>T polymorphism and overall cancer risk." (PMID 29254243, 2017). "In the literature, some mutations and variations in PPARG expression have been associated with cancer in our specie." (PMID 27579030, 2016). "We found that co-culture with PPARγ-deficient macrophages resulted in higher expression of proliferation markers and lower expression of apoptosis markers in cancer cells compared with WT control macrophages." (PMID 27692066, 2016). "The PPARγ pathway served as a novel target to modulate the emergence of MDSCs to reduce the risk of cancer progression and metastasis." (PMID 26625314, 2016). "Gpr132 expression was significantly higher in PPARγ-deficient macrophages compared with control macrophages, either in macrophage cultures alone or in macrophages co-cultured with cancer cells." (PMID 27692066, 2016). "Among the many transcription factor binding sites predicted we found three for peroxisome proliferator-activated receptor-gamma (PPARγ), one for NFκB, and sites for other factors with cancer-associated functions." (PMID 26981774, 2016). "We found 81 non-silent mutations (35 from LG-ESSs and 46 from UUSs) that included 15 putative cancer genes catalogued in cancer-related databases, including PPARG and IRF4 mutations." (PMID 26429873, 2015). "On the other hand, normolipidic diets containing pork fat (7% lard) have cancer-promoting effects (increase in prostatic weight associated with epithelial hyperplasia and increased expression of AR and PPARγ)." (PMID 25912035, 2015). "Increased PPARγ expression has been associated with beneficial effects in cancers including breast and colon, including a reduction in cell proliferation and improved patient prognoses." (PMID 26046374, 2015). "Several studies have focused on the putative association between the various polymorphisms and mutations of the PPARγ gene and the occurrence of cancer." (PMID 23024650, 2012).
cancer (continued). "PPARγ has gained attention in various cancers, where impairment of PPARγ function through mutations has been observed." (PMID 22654559, 2011). "Cancer-retardant activity of CLA has also been reported to be associated with its ability to activate PPARγ." (PMID 22174613, 2011). "Activation of PPARγ also seems to act anti-inflammatory and to hinder proliferation or cause apoptosis in cancer cells." (PMID 19756148, 2009). "In other organs, however, for example, in primary cancers of the lung versus normal lung tissues, decreased expression levels of PPARG were found and associated with poor prognosis." (PMID 19639032, 2009). "Experiments with many different cancer cell lines show thathigh doses of PPARγ inhibitors can cause cell death." (PMID 18509498, 2008). "the action of PPARγ on cell cycle, proliferation, differentiation,and apoptosis seems to depend on the cell type and/or the mutational eventsthat predispose tissue to cancer development”." (PMID 18670615, 2008). "Genepolymorphisms within the human population result in several “loss-of-function”PPARγ variants that are associated withmetabolic diseases (insulin resistance, lipodystrophy) and cancers (e.g., colon, stomach)." (PMID 18596912, 2008). "The discovery of synthetic ligands for this receptor has been driven by the identification of a number of significantdisease settings, in which PPARγ signaling is implicated (inflammation, metabolic disorders, and cancer)." (PMID 18528521, 2008). "The anticancer effects appeared to be cancer cell-specific.A knock-out or loss of function mutation in PPARγ canbe an important risk factor for the incidence of cancer." (PMID 18615188, 2008). "For instance, PPARγ polymorphisms recently have been shownto play a role in determining cancer susceptibility only when patients areabove a certain body mass index threshold." (PMID 18528521, 2008). "There is emerging evidence fora direct role of PPARγ functional mutations in the initiation of several commonhuman cancers, such as colon, prostate, and thyroid." (PMID 18528522, 2008). "Activation of peroxisome proliferator-activated receptor gamma (PPARγ) has been linked to induction of differentiation, cell growth inhibition and apoptosis in several types of human cancer." (PMID 12454768, 2002). "Peroxisome proliferator-activated receptor γ (PPARγ) ligands have been implicated in the growth inhibition and differentiation of certain human cancers with diverse tissue origin." (PMID 11401318, 2001). "Interestingly, a recent study provided direct evidence that HNF-1α is a transcriptional repressor of PPARγ in the liver steatosis-associated cancer models, highlighting a mechanism that seems to be conserved evolutionarily in both mice and humans." (PMID 41614817, 2025). "The signaling of PPARγ has been linked to various diseases, including cancer." (PMID 40603870, 2025). "Notably, the PPARγ agonist rosiglitazone has been shown to delay anorexia and attenuate adipose tissue loss in murine models of cancer cachexia, suggesting that central PPARγ signaling plays a protective role in mitigating anorexia and systemic wasting." (PMID 41476922, 2025). "Furthermore, cancer cachexia causes a reduction of C/EBPα and PPARγ protein expression, which can function as adipogenesis regulation factors." (PMID 38807976, 2024). "Of the three PPAR isoforms, PPARγ is more closely linked to cancer development." (PMID 39450260, 2024). "Although the expression of miRNA-155 in EVs in cancer has been related to the downregulation of PPARγ expression, it could also be associated with visceral fat." (PMID 37047783, 2023). "The activation of PPARG has been associated with beneficial effects on various types of cancer." (PMID 38044948, 2023). "Furthermore, the proliferator-activated receptor γ (PPARγ), the master regulator of adipocyte differentiation, was significantly implicated in inflammation and cancers." (PMID 38137407, 2023).
cancer (continued). "Stromal cells with overexpression of PPARγ displayed metabolic features of cancer-associated fibroblasts, with increased autophagy, glycolysis, and senescence; this supports a catabolic pro-inflammatory microenvironment that metabolically enhances cancer growth." (PMID 35954274, 2022). "MAP2K4 deficiency increased PPARγ expression and promoted cancer cell invasion, which could be reversed via PPARγ inhibition." (PMID 35954274, 2022). "TNBG-5602, a novel anticancer drug candidate, may induce the expression of PPARγ, causing targeted lipotoxicity in cancer tissues." (PMID 35458793, 2022). "Notably, PPARγ negatively regulates NF-κB expression by ligand-dependent transrepression, which was closely associated with cancer cell apoptosis." (PMID 36286423, 2022). "In contrast to COX2 inhibitors, a select group of nonsteroidal antiinflammatory drugs, including ibuprofen, are PPARγ agonists and may account for the difference in cancer incidence with their prolonged use in susceptible tissues." (PMID 36074574, 2022). "Taken together, the PPARγ fusion proteins display a third mode of PPARγ action, as they potentially alter the target gene profile of both parent proteins in the chimeric protein and will target multiple signaling pathways implicated in cancer." (PMID 33716977, 2021). "PPARγ is prone to exert an antiangiogenic effect, which has been known as a hallmark of cancer." (PMID 33777130, 2021). "The genetic predisposition would also explain why certain ethnic groups may be more susceptible to the cancer onset with prolonged usage of PPARγ agonists even though TZDs are generally associated with protective effects against several common cancers." (PMID 33946986, 2021). "In this study, we characterized helix H3 mutations of PPARγ LBD found in various cancers." (PMID 33266062, 2020). "On the other hand, gain-of-function mutations in PPARG have also been found in cancers." (PMID 33266062, 2020). "In fact, in addition to lifestyle interventions, pharmacotherapy with antidiabetic drugs, PPARγ and recombinant growth hormone may decrease the risk of both visceral obesity and cancer." (PMID 33261185, 2020). "Until now numerous investigations were conducted to confirm that cancer cells treatment with NSAIDs are associated with downregulation of oncogenic factors expression and up-regulation of apoptosis pathway with significant role of the PPARγ." (PMID 32710395, 2020). "In addition to the pharmacological regulation of PPARγ in cancers, PPARG genetic alterations resulting in a loss- or gain-of-function have been reported in a variety of cancer types." (PMID 33266062, 2020). "Notably, when the cancer cells were treated with inhibitors of PPARγ phosphorylation, the cancer cells showed more susceptibility to anti-cancer agents inducing DNA damage responses." (PMID 32054125, 2020). "Recently, a meta-analysis indicated that the PPARG rs3856806 C>T polymorphism may increase the susceptibility of overall cancer." (PMID 30838172, 2019). "In addition to its major role in glucose and lipid homeostasis, PPARγ is also associated with inflammatory responses, cardiovascular diseases, neurogenerative diseases, ocular diseases, and cancer." (PMID 31018521, 2019). "Jang Hyun Choi and colleagues at the Ulsan National Institute of Science and Technology, Korea, have found that TRIM25, a protein implicated in cancer and antiviral immune responses, reduces the activity of PPARγ by adding a small regulatory protein that acts as a signal for degradation." (PMID 30323259, 2018). "Several mutations of PPARγ are correlated with cancer initiation." (PMID 29706964, 2018). "We hypothesize that the possible master role of PPARγ in tissue resilience underlies its involvement in distinct diseases from cancer to LOAD." (PMID 29723294, 2018). "These consistent findings demonstrated that PPARG c.1347C>TC>T polymorphism might influence the development of cancer." (PMID 29254243, 2017).
cancer (continued). "We also investigated whether autophagic and PPARγ-mediated pathways could modify a phenotype aspect linked to cancer stem cells (CSCs) population, measured by CD24/CD44 differential expression." (PMID 28932171, 2017). "The nicotine induced up-regulation of WNT/PPAR-gamma (peroxisome proliferator activated receptor gamma) signaling can also regulate cigarette smoke-induced trans-differentiation of lung fibroblast to myofibroblasts that participate forming the cancer-associated stroma." (PMID 28870231, 2017). "Moreover, PPARγ deregulation was detected not only in peripheral tissues linked to lipid metabolism, but also in inflammation and cancer." (PMID 28182091, 2017). "In addition, in a subgroup analysis by origin of cancer cell, evidence of significant association between PPARG c.1347C>T polymorphism and cancer risk was also found among epithelial tumor." (PMID 29254243, 2017). "In this study, we performed a case-control study on the relationship of PPARG c.1347C>T polymorphism with risk of non-small cell lung cancer (NSCLC) and subsequently carried out a meta-analysis to further assess the association between PPARG c.1347C>T and overall cancer." (PMID 29254243, 2017). "PPARγ has been shown to affect multiple aspects of these cancer-associated inflammatory responses." (PMID 28316613, 2017). "Interestingly, PPARγ has been associated with the greatest impact on cancer cell proliferation, survival, and differentiation, and its ligands are associated with anticancer properties." (PMID 28458685, 2017). "Recently, a number of studies focused on the association of PPARG polymorphisms with cancer risk." (PMID 29254243, 2017). "While PPARG has been classically regarded as a master regulator of adipogenesis, more recent studies have implicated it in various cellular processes, including proliferation, apoptosis, angiogenesis, and cancer." (PMID 28275008, 2017). "In conclusion, the findings indicate PPARG c.1347C>T polymorphism may increase the susceptibility of cancer." (PMID 29254243, 2017). "In addition, in a subgroup analysis by the origin of cancer cell, evidence of significant association between PPARG c.1347C>T polymorphism and an increased risk of cancer were also found among epithelial tumor." (PMID 29254243, 2017). "PPARγ loss-of-function mutations have been associated with human cancer development." (PMID 27692066, 2016). "Therefore, PPARγ inactivation in lal−/− MDSCs represents a major mechanism underlying the stimulatory effects of MSDCs on cancer cell proliferation and metastasis." (PMID 26625314, 2016). "Moreover, increased de novo lipogenesis, that is promoted by PPARγ, is now recognized as a metabolic hallmark of cancer cell, including HCC." (PMID 28115925, 2016). "Thus, PPARγ agonists cause cell cycle arrest and promote apoptosis in human cancer cell lines and animal models." (PMID 26091518, 2015). "Thus low levels of adiponectin leads to reduction in PPARγ activity and thus increase the risk of cancer." (PMID 23213569, 2012). "The data also underscore the significant role of PPARγ downstream of Shh in dictating modes of substrate utilization and defining metabolic patterns in these tumors, and possibly other hedgehog-associated cancers." (PMID 22407012, 2012). "With a diverse library in which available therapeutics are included, it may be possible to identify lesser known drug interactions with PPARγ linked to side effects seen with patients taking medications for cancer and neurological diseases." (PMID 21904603, 2011). "Recent evidence has also implicated PPARγ in cell cycle control and cancer progression." (PMID 19300518, 2009). "Further, PPARG rs4684847 was significantly associated with cancer-related mortality; the decrease in risk associated with carrying two of the recessive alleles was observed among females only, although this risk estimate in females was not statistically significant." (PMID 19818126, 2009).